NLRP3 (NLR family pyrin domain containing 3)
Diseases named in the same sentence as NLRP3 in open-access papers (continued):
Sharing a sentence is not in itself a finding about the gene and the disease.
ischemic stroke (continued). "It has been found that NLRP3 expression is increased in microglia of ischemic stroke patients, and increased expression of NLRP3 inflammasomes component proteins and downstream products IL-1β and IL-18 was also observed in the mouse MCAO/R model." (PMID 35937897, 2022). "There is evidence of increased expression and activation of NLRP3 inflammasome in ischemic stroke neurons." (PMID 36091745, 2022). "As the most well-characterized inflammasome, NLRP3 inflammasome is closely related to the inflammatory response and pyroptosis; therefore, the blocking of NLRP3 inflammasome becomes a significant therapeutic target for ischemic stroke." (PMID 35600078, 2022). "On the one hand, the inhibition of the NLRP3 inflammasome is parallel with attenuated neuronal damages in experimental ischemic stroke." (PMID 35688836, 2022). "NLRP3 inflammasomes can produce large amounts of inflammatory factors after ischemic stroke, ultimately leading to neurological dysfunction and neuronal cell death." (PMID 36685518, 2022). "To further validate the effects of PM2.5 on the NLRP3 inflammasome during ischemic stroke, we constructed a NLRP3‐KD1 HMC‐3 cell line and subjected the cells to OGD/R with or without PM2.5 exposure." (PMID 35403328, 2022). "NF‐κB and MAPK signaling pathways promote nucleotide‐binding oligomerization domain (NOD)–like receptor (NLR) Pyrin domain containing 1 and 3 (NLRP1 and NLRP3) inflammasome activation in neurons following ischemic stroke." (PMID 34674376, 2022). "To verify the relationship between PM2.5 exposure and the NLRP3 inflammasome during ischemic stroke, we carried out shRNA‐mediated knockdown of NLRP3 in HMC‐3 cells under ischemic conditions." (PMID 35403328, 2022). "Some studies indicate that resveratrol can inhibit the activation of the NLRP3 inflammasome and the subsequent inflammatory response in ischemic stroke." (PMID 36232980, 2022). "It is demonstrated that not only GSDMD but also NLRC4 and NLRP3 have been identified to promote microglia or neuronal pyroptotic cell death in ischemic stroke." (PMID 35774778, 2022). "Another potential mediator of ischemic stroke that has recently gained attention is the NLRP3 inflammasome, a member of the NLR family of inherent immune cell sensors." (PMID 35328506, 2022). "The NLRP3 inflammasome signal is the initial response that mediates the inflammatory response in the process of ischemic stroke." (PMID 35497095, 2022). "A previous study has demonstrated that curcumin protected against ischemic stroke by modulating microglia/macrophage polarization toward an anti-inflammatory phenotype through NF-κB suppression and NLRP3 inflammasome inhibition." (PMID 36035210, 2022). "More studies are needed to investigate the molecular mechanisms of ROS and NLRP3 inflammasome activation in PM2.5‐induced neuronal injury during ischemic stroke." (PMID 35403328, 2022). "Brain inflammatory responses and NLRP3 inflammasome are activated after ischemic stroke, triggering neuronal cell damage, brain edema, and neurological dysfunction." (PMID 36232980, 2022). "Targeting the upstream and downstream NLRP3 pathways has shown promise in the treatment of ischemic stroke." (PMID 36685518, 2022). "As many research studies have shown, the role of NLRP3 inflammation in exasperating and perpetuating neuroinflammation following an ischemic stroke is well established." (PMID 36297283, 2022). "The NLRP3 inflammasome is involved in the ischemic brain injury process, and its inhibition provides a novel therapeutic target for ischemic stroke." (PMID 36013423, 2022). "The data suggest that Xingxiong injection exerts anti-inflammatory effects after ischaemic stroke via the inhibition of NLRP3 activation." (PMID 35060427, 2022). "NLRP3 inflammasome has been proposed as a critical mediator of microglial M1/M2 polarization post-ischemic stroke." (PMID 35450066, 2022).
ischemic stroke (continued). "The NLRP3 inflammasome has been proposed to mediate inflammatory responses and cell death during ischemic stroke." (PMID 35454994, 2022). "Early evidence showed that activators of NLRP3 played a remarkable role in inflammation process of ischemic stroke, and several studies have explored the detailed mechanism of inflammatory response in this process." (PMID 36204568, 2022). "Given our previous study that Nrf2 inhibits the inflammatory cascade caused by the NLRP3 inflammasome, thereby alleviating cerebral I/R injury in Sprague–Dawley (SD) rats, the effect of HIPK2 on inflammation in ischemic stroke is worthy of inquiry." (PMID 36362432, 2022). "In a table, we outline several compounds that have a suppressive effect against the activation of NLRP3 inflammasome and, therefore, can represent the protagonists of the new frontiers of pharmacological therapy of ischemic stroke." (PMID 36297283, 2022). "The data suggested that CGGE exerted an anti-inflammatory effect after ischemic stroke by inhibiting NLRP3 activation." (PMID 36091745, 2022). "It seems more advantageous to identify therapeutic strategies aimed at upmodulating or downmodulating the NLRP3 inflammasome pathway at several levels than intervening on other physiopathological mechanisms characteristic of ischemic stroke." (PMID 36297283, 2022). "Inversely, NF-κB signaling and MAPK signaling promote the NLRP3 inflammasome activation during ischemic stroke in neurons." (PMID 35300578, 2022). "Particularly, NLRP1 and NLRP3 inflammasome-mediated neuronal pyroptosis performed an increasingly crucial role in the course of ischemic stroke." (PMID 34646128, 2021). "There was a trend of association between a higher level of serum concentration of NLRP3 and an increased risk of MBE after ischemic stroke, possibly confounded by the severity of stroke, which is worth further validation in large cohort studies." (PMID 34493232, 2021). "Our results furthermore suggest that ISO pretreatment can reduce ischemic stroke-induced retinal injury under diabetic conditions by inhibiting NLRP3 inflammasome activation." (PMID 34305534, 2021). "The total data hint that NLRP3-inflammasome signaling cascade repression with MCC950 has salutary actions in ischemic stroke models." (PMID 34443594, 2021). "Targeted intervention on NLRP3’s activation mode, action mode and itself is the current research hotspot for the treatment of inflammatory response after ischemic stroke." (PMID 34526897, 2021). "It has also been documented that myrrh exerts a neuroprotective effect by regulating the TXNIP/NLRP3 axis in ischemic stroke to reduce ROS-mediated ferroptosis." (PMID 34059091, 2021). "In brief, our findings suggested that the anti-pyroptosis effect of EE after ischemic stroke was associated with the inhibition of the NF-κB p-65 signaling pathway and the reduced expression levels of NLRP1 and NLRP3 inflammasome-related proteins." (PMID 34646128, 2021). "It was worth noting that NLRP1 and NLRP3 inflammasomes were reported to be involved in ischemic stroke." (PMID 34646128, 2021). "After ischemic stroke, the NLRP3 inflammasome can produce numerous proinflammatory cytokines, mediating nerve cell dysfunction and brain edema and ultimately leading to nerve cell death once activated." (PMID 34059091, 2021). "There is a strong indication that BTK is mandatory for NLRP3 inflammasome stimulation, and therefore is anticipated to be a potential therapeutic target in cases of ischemic stroke." (PMID 34443594, 2021). "The mechanisms are associated with suppressing TLR4/NF-κB pathway and NLRP3 inflammasome and enhancing LC3-II and Beclin-1 expressions after ischemic stroke." (PMID 34257822, 2021). "Previous studies have reported that the NLRP3 inflammasome is involved in neuronal cell death in ischemic stroke." (PMID 33735403, 2021).
ischemic stroke (continued). "In the present study, our in vivo and in vitro data indicated that curcumin greatly inhibited the activation of NLRP3 inflammasome induced by ischemic stroke." (PMID 34630845, 2021). "Mounting evidence has indicated that the NLRP3 inflammasome played a prominent role in the pathogenesis and progression of ischemic stroke." (PMID 33967935, 2021). "Recent studies have identified NLRP3 inflammasome-mediated ischemic stroke as a new mechanism that leads to neuron and glial cell death after brain injury." (PMID 34059091, 2021). "In a murine model of ischemic stroke, sinomenine (10–20 mg/kg, ip) provided salutary effect by attenuating expression of NLRP3 and ASC, decrementing cleaved caspase-1 and IL-1β levels, as well as IL-6, IL-18, and TNF-α concentrations." (PMID 34443594, 2021). "This suggests that TXNIP-mediated activation of the NLRP3 inflammasome is a key factor in ischemic stroke." (PMID 34059091, 2021). "The NLRP3 inflammasome is responsible for exerting adverse effects on neurons after ischemic stroke." (PMID 34059091, 2021). "Nucleotide-binding oligomerization domain-like receptor pyrin domain-containing protein 3 (NLRP3) plays an important role in mediating inflammatory responses during ischemic stroke." (PMID 33531049, 2021). "To date, the relationship between caspase-12 and the NLRP3 inflammasome in ischemic stroke is unclear." (PMID 32788872, 2020). "ROS accumulation was able to activate the NLRP3 inflammasome, and the activated NLRP3 inflammasome subsequently mediated neuroinflammation during ischaemic stroke by secretion IL‐1β." (PMID 32990414, 2020). "Following ischemic stroke, the generation of ROS can activate both cerebral inflammatory reactions and NLRP3 inflammasome, triggering neuronal cell injury, brain edema, and neural dysfunction." (PMID 32581721, 2020). "Increasing evidence has suggested that NLRP3 inflammasome is a crucial mediator of neuroinflammation and plays an important role in the progression and pathogenesis of ischemic stroke." (PMID 32581721, 2020). "Several other molecular inhibitors also have beneficial effects by reducing the expression of NLRP3 in ischemic stroke." (PMID 32581721, 2020). "Currently, there are a series of molecules that play a neuroprotective role in ischemic stroke models by inhibiting the NLRP3 inflammasome pathway." (PMID 32581721, 2020). "NLRP3 inflammasome plays a crucial role in ischemic stroke and it has been found that it is increased in ischemic conditions." (PMID 32650482, 2020). "Mitochondrial dysfunction also exerted a crucial role in the activation of NLRP3 inflammasome after OGD/R in microglia, and mitochondrial protector was able to suppress the NLRP3 inflammasome activation in ischemic stroke rats." (PMID 32581721, 2020). "Accumulating evidence suggests that NLRP3 inflammasome activation plays an important role in ischemic stroke injury." (PMID 32788872, 2020). "In an ischemic stroke, oxidative stress is the main initiator and it has been shown that NLRP3 activation is achieved by means of a thioredoxin-interacting protein (TXNIP) (endogenous inhibitor of TRX), which is activated by oxidative stress." (PMID 32650482, 2020). "In this mini review article, we will summarize the structure, assembly, and regulation of NLRP3 inflammasome, the role of NLRP3 inflammasome in ischemic stroke, and several treatments targeting NLRP3 inflammasome in ischemic stroke." (PMID 32581721, 2020). "In summary, many medicants have positive effects on improving neurological dysfunction, infarct volume, and cerebral edema in ischemic stroke model via suppressing NLRP3 pathways." (PMID 32581721, 2020). "Several other therapeutic methods have been used to treat the ischemic stroke animal models by suppressing NLRP3 inflammasome." (PMID 32581721, 2020).
ischemic stroke (continued). "Accumulating amounts of evidence have indicated that NLRP3 inflammasome activation was closely related with post-ischemic inflammation after stroke, which was critical in neuronal cell death in ischemic stroke." (PMID 32153398, 2020). "Our results indicate that Tet exerts neuroprotective effects against ischemic stroke injury partly through inhibiting the activation of the NLRP3 inflammasome via upregulating Sirt-1." (PMID 32419986, 2020). "In summary, the study of the effect of NLRP3 inflammasome and its potential mechanism in ischemic stroke will provide new therapeutic targets for the treatment of ischemic stroke." (PMID 32581721, 2020). "More importantly, the activation of the NLRP3 inflammasome aggravates ischemic stroke injury, whereas NLRP3 depletion reduces brain damage after cerebral ischemia." (PMID 32625078, 2020). "The activation of NLRP3 inflammasome has been reported to involve in the pathophysiology of various neurological disorders, such as ischemic stroke, intracerebral hemorrhage, and traumatic brain injury." (PMID 32703306, 2020). "Taken together, all of these molecular inhibitors can inhibit the expression of NLRP3 and have a neuroprotective effect on ischemic stroke." (PMID 32581721, 2020). "Several molecular inhibitors via inhibiting NOD-like receptor pyrin domain containing 3 (NLRP3) inflammasome in ischemic stroke." (PMID 32581721, 2020). "Ker Gawl., has been shown to have protective effects after ischemic stroke by inhibiting NLRP3, IL-1β, caspase-1 and TXNIP in vitro and in vivo." (PMID 32650482, 2020). "Nafamostat mesilate (NM), as a wide-spectrum serine protease inhibitor, has immune-modulatory impacts on ischemic stroke rats, which is related to the suppression of NLRP3 inflammasome and NF-κB signaling pathway." (PMID 32581721, 2020). "Previous studies have demonstrated that ischemic stroke can induce microglia activation and promote NLRP3 expression, resulting in neuronal cell death." (PMID 32419986, 2020). "Here, we summarize the current understanding regarding the structure, assembly, and regulation of the NLRP3 inflammasome, its potential roles in ischemic stroke, and recent treatments targeting at suppressing NLRP3 inflammasome in stroke." (PMID 32581721, 2020). "Among them, the NLRP3 inflammasome is the most typical inflammasome, which can detect cell damage and mediate inflammatory response to tissue damage in ischemic stroke." (PMID 32581721, 2020). "Recent findings demonstrated that NLRP3 inflammasome play a crucial role in regulating inflammatory responses in the pathological process of ischemic stroke." (PMID 32908485, 2020). "The further understanding of the mechanism of NLRP3 inflammasome in patients with ischemic stroke will provide novel targets for the treatment of cerebral ischemic stroke patients." (PMID 32581721, 2020). "Among multiple inflammasome-forming proteins, NLRP3 has been reported to regulate neuroinflammation and neuronal death in ischemic stroke." (PMID 33153475, 2020). "MCC950 is a novel, selective small-molecule inhibitor that specifically blocks NLRP3 activation, whereby it attenuates inflammation and brain injury after intracerebral hemorrhage and ischemic stroke." (PMID 32703306, 2020). "It has been shown that downregulation of NLRP3 inflammasome has a neuroprotective effect against ischemic strokes." (PMID 32419986, 2020). "On the one hand, the discovery of NLRP3 inflammasome provides a new way to study the molecular mechanism of ischemic stroke." (PMID 32581721, 2020). "MCC950 is an NLRP3-inflammasome inhibitor that has been shown to exert positive effects on ischemic stroke models." (PMID 32581721, 2020). "A recently discovered inflammasome, nod-like receptor protein 3 (NLRP3), plays a key role in the mediation of inflammatory responses in ischemic stroke." (PMID 32625078, 2020).
ischemic stroke (continued). "In conclusion, QNDP had neuroprotective effects against cerebral ischemia via inhibiting NLRP3 inflammasome signaling pathway, and was a potential candidate for the future treatment of ischemic stroke." (PMID 32153398, 2020). "NLRP3 was mainly reported to express in microglia after both ischemic stroke and hemorrhagic stroke." (PMID 32625078, 2020). "The NLRP3 inflammasome, also known as cryopyrin or NALP3, has an essential role in the damage caused by inflammation associated with ischemic stroke and type 2 diabetes mellitus (T2DM)." (PMID 31174550, 2019). "LED therapy also downregulated the expression of proinflammatory cytokines IL-18 and IL-1β and attenuated the NLRP3 inflammasome in an ischemic stroke model." (PMID 31287006, 2019). "We find that ischemic stroke initiates NLRP3 inflammasome activation, which is inhibited by meisoindigo treatment." (PMID 31920554, 2019). "This in turn leads to the NLRP3-mediated inflammatory response, affecting the host’s immune balance and exacerbating the effects of ischemic stroke." (PMID 31174550, 2019). "Taken together, these data indicate that inhibition of NLRP3-inflammasome with MCC950 has therapeutic potential in ischemic stroke models." (PMID 29654318, 2018). "Accordingly, we found evidence of NLRP3 inflammasome activity within ischemic stroke infarcts during the chronic stage of liquefactive necrosis by way of a significant elevation of IL-18 at four and eight weeks following stroke." (PMID 30417081, 2018). "It has been confirmed that NLRP3 inflammasome is activated since the onset of ischemic stroke, and treatments targeting NLRP3 inflammasome are found to be promising for the treatment of stroke." (PMID 29662437, 2018). "The NLRP3 inflammasome has been proved to play an important role in detecting cellular damage and mediating inflammatory responses to tissue injury during ischemic stroke." (PMID 27652274, 2016). "Collectively, these data strongly confirmed that NLRP3 represents a potential therapeutic target in the management of ischemic stroke." (PMID 27127546, 2016). "Our results thus add to the growing body of evidence indicating that ischemic stroke-induced brain damage can be ameliorated by modulating the NLRP3 inflammasome axis." (PMID 26473731, 2015). "However, there is still no clear evidence confirming the correlation between TXNIP and the NLRP3 inflammasome in ischemic stroke." (PMID 39690856, 2025). "Considerable studies support that the NLRP3 inflammasome is active in ischemic stroke, inducing an inflammatory response that may be linked to BBB disruption." (PMID 40260133, 2025). "Accumulating evidence indicates that acupuncture may substantially decrease neurological impairment score and cerebral infarction volume in ischemic stroke rats while also inhibiting NLRP3 and Caspase-1 expression, thereby providing a neuroprotective effect." (PMID 40260133, 2025). "In addition, NLRP3 inflammasome activation has been related to several cerebrovascular diseases, including ischemic stroke." (PMID 39753298, 2025). "Hence, studying the relationship between NLRP3 and early cognitive dysfunction in elderly patients with ischemic stroke after neurointerventional procedures is of great importance." (PMID 40417311, 2025). "Importantly, it was demonstrated that genistein exhibits a significant overlap in its therapeutic effects on ischemic stroke models, affecting the Nrf2, NF-κB, and NLRP3 pathways." (PMID 41433336, 2025). "Furthermore, NLRP3 and the use of esketamine were identified as relevant factors for the development of cognitive dysfunction in elderly patients with ischemic stroke undergoing neurointerventional surgery." (PMID 40417311, 2025).